CRP (C-reactive protein)
Diseases named in the same sentence as CRP in open-access papers (continued):
Sharing a sentence is not in itself a finding about the gene and the disease.
coronary artery aneurysms (24 papers, 2004 to 2025). "A previous study assessed that patients with Kawasaki disease shock syndrome either have a higher risk of developing coronary artery aneurysms and higher blood CRP levels, WBC, and neutrophil counts." (PMID 38031949, 2023). "Black children with KD have higher levels of inflammation during their KD (C-Reactive Protein and Erythrocyte Sedimentation Rate) which are thought to predispose them to poor clinical outcomes (poor IVIG response and higher coronary artery aneurysms)." (PMID 37441576, 2023). "One child with coronary aneurysms received Infliximab 5 days after the second dose of IV Ig because of persistent elevated CRP." (PMID 30021610, 2018). "We and others have shown that high-sensitivity C-reactive protein is elevated in KD patients with coronary aneurysms late after the acute illness and implicate the persistence of chronic low-grade inflammation in these patients." (PMID 18466622, 2008). "In comparison to an Italian study that shows how higher values of CRP may play a crucial role in determining the development of coronary complications, our analysis revealed no laboratory value or any distinct clinical symptom that can be correlated with the development of coronary aneurysms." (PMID 27643389, 2014). "Even though there is a relationship between Annexin A1 and CRP, blood CRP levels are not directly correlated with coronary artery aneurysm development." (PMID 38031949, 2023). "In KD children, circulating resistin levels are higher in those with coronary artery aneurysm compared with controls and KD without coronary artery aneurysm, and positively correlated with CRP." (PMID 33081064, 2020). "In this study, we did not observe increased CRP levels in those patients with coronary aneurysms." (PMID 15482602, 2004). "Inflammatory markers such as CRP, ESR, platelet count, hemoglobin, and albumin are key predictors of coronary artery aneurysm development, but we did not identify a significant modifying effect of biological sex." (PMID 40756547, 2025). "Then, we discovered that he had AAC, which was well managed by intravenous immunoglobulin (IVIG) as the fever subsided, C-reactive protein (CRP) decreased, and repeated abdominal ultrasound showed a decrease in gallbladder thickness without any evidence of coronary artery aneurysms." (PMID 38161523, 2023).
diabetic foot ulcer (24 papers, 2014 to 2026). "This study shows that high CRP levels and poor glycemic control are strongly associated with severe diabetic foot ulcers, delayed healing, and a greater need for amputation." (PMID 41367458, 2025). "Association between HbA1C levels and C-reactive protein (CRP) in patients with diabetic foot ulcer (n = 120)." (PMID 41367458, 2025). "In patients with amputation for a diabetic foot ulcer, an elevated serum CRP level can predict mortality since the preoperative/postoperative CRP differences were associated with increased mortality." (PMID 40002826, 2025). "Another inflammatory marker, high sensitivity C-reactive protein levels, were higher in the diabetic patients with diabetic foot ulcers, a complication closely associated with diabetic neuropathy, than those in diabetic patients without foot ulcers." (PMID 37762893, 2023). "Therefore, the present study aims to investigate the association between CRP levels, HbA1c values, and diabetic foot ulcer outcomes." (PMID 41367458, 2025). "Fibrinogen levels have been shown to correlate with CRP levels, neutrophil and blood leukocyte counts, and independently predict the risk of amputation in diabetic foot ulcers, suggesting its potential utility in assessing disease severity and monitoring progression." (PMID 37559005, 2023). "Procalcitonin is significantly higher in infected diabetic foot ulcers, and compared to CRP, procalcitonin has higher sensitivity and specificity in infected diabetic feet." (PMID 38673584, 2024). "The increasing risk of amputation due to diabetic foot ulcer calls for new therapeutic options; for that, we determined the role of IMMUNEPOTENT CRP (ICRP) and its parts in the wound healing process of superficial wounds in diabetic BALB/c mice." (PMID 38835975, 2024). "An Important concern is the site of action of a treatment; in our case, the main site of action was in skin tissue in a prediction for humans, suggesting a possible treatment employing exosomes isolated from IMMUNEPOTENT CRP in diabetic foot ulcers." (PMID 37240318, 2023). "PCT has also been shown to play a major role in diagnosis of diabetic foot ulcers, and its role can be even more important than CRP." (PMID 31555767, 2019). "Similarly, increased CRP level has also been observed among diabetic foot ulcer patients." (PMID 25184511, 2014). "In summary, this systematic review evaluated the role of ESR, CRP, PCT, and WCC in the diagnosis of diabetic foot ulcers according to the IWGDF and PEDIS classification system." (PMID 35476639, 2022). "Cut-off value, sensitivity, specificity, and AUC for ESR, CRP, PCT, and WCC for IWGDF grade 2 versus grade 3 diabetic foot ulcers." (PMID 35476639, 2022). "Cut-off value, sensitivity, specificity, and AUC for ESR, CRP, PCT, and WCC for IWGDF grade 1 versus grade 2 diabetic foot ulcers." (PMID 35476639, 2022). "ESR, CRP and PCT had moderate value for predicting class of diabetic foot ulcer according to ROC analysis." (PMID 31555767, 2019). "In a systematic review, they evaluated the roles of ESR, CRP, platelets, and WBC in the diagnosis of diabetic foot ulcers according to the International Working Group on Diabetic Foot and Perfusion, Extent (size), Depth (tissue loss), Infection, Sensation classification system." (PMID 41300930, 2025). "From the analysis, they concluded that CRP is the ideal marker for distinguishing grade 2 diabetic foot ulcers from non-infected diabetic foot ulcers, especially in smaller communities lacking access to advanced imaging modalities." (PMID 41300930, 2025). "Known infection markers include white blood cells (WBCs), the erythrocyte sediment rate (ESR), C-reactive protein (CRP), and procalcitonin, but they are not specific to diabetic foot ulcers." (PMID 38673584, 2024). "CRP is significantly higher in patients with diabetic foot ulcers, but it is known to be diagnostically more effective with procalcitonin rather than CRP alone." (PMID 38673584, 2024).
diabetic foot ulcer (continued). "Finally, although PCT is a promising inflammatory marker, it seems that it is not more effective and useful than other classic markers (such as ESR or CRP) for classifying the infected diabetic foot ulcer from non-infected ones." (PMID 24696696, 2014).
Disseminated intravascular coagulation (24 papers, 2011 to 2025). Disseminated intravascular coagulation is characterized by the widespread activation of coagulation, which results in the intravascular formation of fibrin and ultimately thrombotic occlusion of small and midsize vessels. "The concentration of ethanol in blood and urine and the blood c-reactive protein values were analyzed, and a state of disseminated intravascular coagulation (DIC) was also found." (PMID 40029560, 2025). "In severe cases, patients may have a high fever, increased levels of C-reactive protein (CRP), cytopenia, abnormal levels of coagulation parameters, disseminated intravascular coagulation (DIC), and damage to several organs, which can be fatal." (PMID 34253862, 2021). "The development of disseminated intravascular coagulation (DIC) in patients with more severe interstitial pneumonia could partially explain the stronger relationship of D-dimer and hsTnT with the mortality risk compared to CRP." (PMID 33753759, 2021). "On blood tests, hemoglobin (Hb) was 11.8 g/dl, C-reactive protein (CRP) was 5.54 mg/dl, soluble interleukin-2 receptor (sIL-2R) was 3732 U/ml (standard 144–518 U/ml), and a tendency to disseminated intravascular coagulation (DIC) (PLT 5.4 x 104/μl, FDP 156 μg/ml, D-dimer 80 μg/ml) was seen." (PMID 28068928, 2017).
glioma (24 papers, 2014 to 2025). A benign or malignant brain and spinal cord tumor that arises from glial cells (astrocytes, oligodendrocytes, ependymal cells). "A previous study reported that elevated circulating levels of IL-6, IL-8, IL-17, TNF-α, TGF-β, and CRP are significantly linked to an increased risk of glioma." (PMID 38259287, 2023). "Some possible mechanisms elucidating the increased risk and poor prognosis of high CRP levels in gliomas have been reported." (PMID 33747971, 2021). "This study aimed to investigate the association of high-sensitivity C-reactive protein (hsCRP) and N-terminal pro-B-type natriuretic peptide (NT-proBNP) serum concentrations with cognitive functions of glioma and meningioma patients." (PMID 32461966, 2020). "Our results indicate that increased circulating IL‐6, IL‐8, IL‐17, TNF‐α, TGF‐β, and CRP levels are significantly associated with increased glioma risk." (PMID 31599129, 2019). "Our meta‐analysis indicates that increased circulating IL‐6, IL‐8, IL‐17, TNF‐α, TGF‐β, and CRP levels are significantly associated with increased glioma risk." (PMID 31599129, 2019). "The results showed that increased circulating IL‐6, IL‐8, IL‐17, TNF‐α, TGF‐β, and CRP levels before treatment are significantly associated with glioma risk." (PMID 31599129, 2019). "Thus, before initiating treatment, high levels of IL-6, IL-8, IL-17, IL-33, TNF-α, TGF-β, and CRP in the circulation are strongly associated with increased glioma stem cell activity that potentially leads to glioma progression and greater invasiveness." (PMID 35054779, 2022). "Additionally, a meta-analysis found that the CRP value is associated with glioma risk, as well as with a poor prognosis." (PMID 33747971, 2021). "Moreover, our results indicated that increased circulating IL‐6, IL‐8, IL‐17, TNF‐α, TGF‐β, and CRP levels are significantly associated with increased glioma risk." (PMID 31599129, 2019). "A meta-analysis showed that increased CRP levels have been significantly associated with higher glioma risk, and also, CRP may serve a powerful biomarker for a worse prognosis in glioma patients, as well as an independent predictor for the overall survival in subjects with glioblastoma." (PMID 37873776, 2023). "This study systematically explored for the first time the combined effect of AVP, OT, β-EP and serum inflammatory factors (TNF-α, IL-6, CRP) in postoperative nerve injury and prognosis of patients with glioma, filling the research gap in this field." (PMID 41244525, 2025). "Case study of 35 patients with glioma brain tumors reported that neuroinflammatory markers, like procalcitonin and C-reactive protein, are prognosis markers of glioma, further confirming the connection between neuroinflammation and brain tumor." (PMID 37335084, 2023). "The DASH diet can maintain a lower level of C-reactive protein in the cycle, exert anti-inflammatory effects, and thus prevent the development of glioma." (PMID 38068744, 2023). "On the other hand, our results showed a poor prognostic outcome in glioma patients expressing high levels of circulating IL‐6 and CRP." (PMID 31599129, 2019). "Regarding CRP, four studies including 466 glioma patients were selected for the prognostic analysis." (PMID 31599129, 2019). "The expression of circulating CRP levels was significantly correlated with poor OS in glioma patients, and the pooled HR was 2.02 (95% CI: 1.52‐2.68; P = .000)." (PMID 31599129, 2019). "The results from our present meta‐analysis showed a high risk of developing glioma with elevated levels of CRP and a poor prognostic outcome in glioma patients expressing high levels of CRP." (PMID 31599129, 2019). "On the other hand, our results showed that circulating IL‐6 [HR 1.10 (95% CI: 1.05‐1.16; P = .000)] and CRP [HR 2.02 (95% CI: 1.52‐2.68; P = .000)] levels were highly correlated with a poor overall survival (OS) rate in glioma patients." (PMID 31599129, 2019).
glioma (continued). "A recent meta-analysis proposed that circulating interleukin 6 (IL-6) and C-Reactive Protein (CRP) could potentially serve as robust biomarkers for predicting poor prognosis in patients with glioma." (PMID 38784036, 2024). "Furthermore, circulating IL-6 and CRP have the potential to act as potent prognostic biomarkers for unfavorable outcomes in glioma patients." (PMID 38259287, 2023). "Regarding CRP, four studies including 466 glioma patients were selected." (PMID 31599129, 2019). "Determination of the levels of circulating IL‐6 and CRP might aid in predicting the clinical outcome in glioma patients." (PMID 31599129, 2019). "In conclusion, our meta‐analysis suggested that circulating IL‐6 and CRP levels may serve as powerful biomarkers for a poor prognosis in glioma patients." (PMID 31599129, 2019). "Moreover, our meta‐analysis suggests that circulating IL‐6 and CRP may serve as powerful biomarkers for a poor prognosis in glioma patients." (PMID 31599129, 2019). "Furthermore, the circulating IL‐6 or CRP level may be a reliable prognostic indicator in glioma patients." (PMID 31599129, 2019). "Moreover, it suggests that circulating IL‐6 and CRP may serve as powerful biomarkers for a poor prognosis in glioma patients." (PMID 31599129, 2019). "This study aimed to investigate the relationship between serum inflammatory markers (TNF-α, IL-6, CRP) and cerebrospinal fluid (CSF) cytokine levels (AVP, OT, β-EP) with the severity of postoperative neurological injury and prognosis in patients with glioma." (PMID 41394380, 2025). "Inflammatory markers like IL-6, CRP, SAA, and TNF-α can induce M2 macrophage polarization, promoting glioma progression and playing an essential role in glioma development." (PMID 41244525, 2025). "The purpose of this study is to explore the clinical value of high-quality nursing in concurrent radiotherapy and chemotherapy after glioma surgery and its influence on the stress indicators such as cortisol (Cor), adrenocorticotrophic hormone (ACTH), and C-reactive protein (CRP)." (PMID 35126950, 2022). "Importantly, a study showed that CRP tended to be lower in meningioma, and also, there was a CRP increase in meningioma, glioma, and brain metastatic tumors, but it was not significant." (PMID 37873776, 2023). "In contrast, CRP levels increased in patients with GBM (median pre-treatment = 0.1 mg/dl vs. before cycle 2 = 0.195 mg/dl, p = 0.039), while no significant change could be observed in WHO grade II–III glioma (median pre-treatment = 0.06 mg/dl vs. before cycle 2 = 0.13 mg/dl, p = 0.886)." (PMID 33956203, 2021).
hemorrhage (24 papers, 2016 to 2026). Loss of blood from the vascular compartment to the exterior or into nonvascular body space as a result of rupture or severance of the blood vessels. "Furthermore, in prior study of 321 ECMO patients lower values of C-reactive protein associated with hemorrhage, corroborating the complex relationship between inflammation and bleeding in ECMO patients." (PMID 40909455, 2025). "Post-ICH studies reveal CRP concentrated in blood vessels and inside activated astrocytes and neurons surrounding the hemorrhage site." (PMID 40649973, 2025). "Among them, six variables were selected by a feature selection method: induction chemotherapy (CTx), hemorrhage, infection, C-reactive protein, blood urea nitrogen, and lactate dehydrogenase." (PMID 37762881, 2023). "But in the presence of hemorrhage, we show that reduction in CRP after radiation is further lowered by CI." (PMID 28934227, 2017). "CRP and IL-6 levels were markedly elevated in patients with hemorrhage or fatal outcomes." (PMID 41901712, 2026). "As the D30 prognostic factor predicts a short survival duration, infection at the time of admission, patient eligibility for intensive CTx or low-dose CTx, including HMA and LDAR, the presence of hemorrhage, and laboratory parameters like CRP, BUN, and LDH were important prognostic factors." (PMID 37762881, 2023). "This further shows a non-statistically significant trend of increased CRP and Hcy levels being associated with a larger hemorrhage size." (PMID 30613458, 2018). "In addition, the location of the lesion, histological types, stage, smoking history, HDLC, and CRP level positively correlated with EBB-induced hemorrhage as assessed by univariate analysis." (PMID 30031394, 2018). "Immunostaining confirmed strong CRP in endothelial cells and inflammatory infiltrates around newly formed microvessels in UNC plaques, whereas fibrous plaques were CRP-negative, and hemorrhagic plaques showed only weak staining." (PMID 40649973, 2025). "The score and its parameters are based on a retrospective analysis in a single center setting and a prospective evaluation in the same center and includes the standard PRISM score and three additional variables (CRP, GVHD and hemorrhage)." (PMID 37810960, 2023). "The final logistic model comprised 4 independent predictors (RPP, CRP, GCS, hemorrhage volume)." (PMID 38911585, 2024). "In addition, the CRP can also rise secondary to non-infective conditions including respiratory distress syndrome, meconium aspiration syndrome, stressful delivery, perinatal asphyxia or intraventricular haemorrhage meaning it is poorly specific." (PMID 30509228, 2018).